MTHFD1L (methylenetetrahydrofolate dehydrogenase (NADP+ dependent) 1 like)
Description:
May provide the missing metabolic reaction required to link the mitochondria and the cytoplasm in the mammalian model of one-carbon folate metabolism complementing thus the enzymatic activities of MTHFD2.
Synonyms: FTHFSDC1; DKFZP586G1517; FLJ21145; MTC1THFS; dJ292B18.2
Tractability: PROTAC: ubiquitination databases record sites on it; its protein half-life has been measured.
Target class: Enzyme; Ligase
Gene: Protein-coding gene on chromosome 6 (150,865,679 to 151,101,887, forward strand). Ensembl gene ENSG00000120254.
Subcellular location: Mitochondrion
Subcellular location (Human Protein Atlas): Mitochondria
Pathways (Reactome):
Metabolism: Metabolism of folate and pterines
Gene Ontology:
Molecular function: ATP binding; formate-tetrahydrofolate ligase activity; protein homodimerization activity; methylenetetrahydrofolate dehydrogenase (NADP+) activity
Biological process: 10-formyltetrahydrofolate biosynthetic process; folic acid-containing compound metabolic process; formate metabolic process; embryonic neurocranium morphogenesis; embryonic viscerocranium morphogenesis; neural tube closure; carboxylic acid biosynthetic process; formate biosynthetic process; tetrahydrofolate interconversion; tetrahydrofolate metabolic process
Cellular component: membrane; mitochondrion; cytosol; mitochondrial matrix
Genetic constraint (gnomAD): Loss-of-function variants: 65 observed, 93.39 expected, observed/expected ratio (o/e) 0.7, 90% interval 0.57 to 0.86. The upper end of that interval is the gene's LOEUF score, 0.86, which puts it in group 3 of 6, group 1 being the genes least tolerant of losing a copy. Missense variants: 941 observed, 1,049.2 expected, observed/expected ratio (o/e) 0.9, 90% interval 0.85 to 0.95. Synonymous variants: 365 observed, 391.9 expected, observed/expected ratio (o/e) 0.93, 90% interval 0.85 to 1.02.
Homologues: Orthologues: macaque MTHFD1L (97% identical), rabbit MTHFD1L (91% identical), dog MTHFD1L (89% identical), mouse Mthfd1l (88% identical), pig MTHFD1L (88% identical), rat Mthfd1l (88% identical), guinea pig MTHFD1L (87% identical), tropical clawed frog mthfd1l (72% identical), zebrafish mthfd1l (65% identical). Paralogues in human: MTHFD1 (59% identical), MTHFD2 (8% identical), MTHFD2L (7% identical).
Diseases named in the same sentence as MTHFD1L in open-access papers:
MTHFD1L is named in the same sentence as 45 diseases in open-access papers, as found by Europe PMC text mining. Sharing a sentence is not in itself a finding about the gene and the disease. The quoted sentences say what the papers report.
colon cancer (9 papers, 2019 to 2025). "Fischl and colleagues reported that hnRNPC overexpression establishes specific alternative cleavage and polyadenylation (APA) profiles in metastatic colon cancer cells by regulating poly(A) site selection in cancer-implicated genes like MTHFD1L." (PMID 41429980, 2025). "Methylenetetrahydrofolate dehydrogenase 1-like (MTHFD1L) has been shown to be associated with colon cancer cell proliferation, colony formation and invasion." (PMID 33605411, 2021). "MTHFD1L has been associated with colon cancer cell proliferation, colony formation, and invasion." (PMID 38625586, 2024). "We identify that overexpression of hnRNPC has a critical role in the establishment of APA profiles characteristic for metastatic colon cancer cells, by regulating poly(A) site selection in a subset of genes that have been implicated in cancer progression including MTHFD1L." (PMID 31147722, 2019). "Another study reported that MTHFD1L was involved in colorectal cancer progression, and blocking MTHFD1L reduces the growth of colon cancer cells, thus providing an avenue to target this enzyme with small molecule inhibitors." (PMID 33605411, 2021). "A high expression level of MTHFD1L is also reported in patients with primary CRC, and downregulation of MTHFD1L suppressed the colon cancer cell proliferation and invasion rate." (PMID 34200820, 2021). "We found that elevated levels of hnRNPC in metastatic-derived colon cancer cells are responsible for driving CR- and UTR-APA of a subset of genes including MTHFD1L, which has been strongly linked to cancer progression." (PMID 31147722, 2019). "In addition, elevated levels of hnRNP C in metastatic colon cancer cells drive coding region (CR) and UTR APA of a group of genes, including methylenetetrahydrofolate dehydrogenase (NADP+-dependent) 1-like (MTHFD1L), and these changes are closely associated with cancer progression." (PMID 35395937, 2022). "To do so, we quantitatively determined the levels of the TNMD, MTHFD1L, and KIF14 proteins in healthy primary mammary epithelial cells (PMECs), a TNBC cell line (MDA-MB-231), and a colon cancer cell line (CT-26)." (PMID 39409999, 2024).
colorectal cancer (8 papers, 2018 to 2024). A primary or metastatic malignant neoplasm that affects the colon or rectum. "MTHFD1L was highly expressed in tongue squamous cell carcinoma, colorectal cancer, bladder cancer, and osteosarcoma and associated with poor disease prognosis." (PMID 35693982, 2022). "Compared with patients with low MTHFD1L expression, patients with high MTHFD1L expression of colorectal cancer have a higher risk of death (HR=3.927, 95%CI: 1.518-10.16).Survival analysis indicating that MTHFD1L is a potential prognostic biomarker." (PMID 32368304, 2020). "In summary, this study indicated that MTHFD1L is highly expressed in colorectal cancer and is associated with poor prognosis." (PMID 32368304, 2020). "The gene MTHFD1L coding for methylenetetrahydrofolate dehydrogenase 1–like is significantly overexpressed in the colorectal cancer phenotype." (PMID 39484215, 2024). "MTHFD1L is also involved in the progression of esophageal cancer, bladder cancer, colorectal cancer, and tongue cancer." (PMID 35681277, 2023). "Patients with increased MTHFD1L expression had a poorer survival rate in both colorectal cancer (CRC) and hepatocellular carcinoma." (PMID 35693982, 2022). "MTHFD1L is overexpressed in multiple solid cancers, such as colorectal cancer, tongue squamous cell carcinoma, esophageal squamous cell carcinoma." (PMID 33605411, 2021). "In this study, downregulation of MTHFD1L also inhibited the proliferation of colorectal cancer cells." (PMID 32368304, 2020). "MTHFD1L promotes proliferation and metastasis of colorectal cancer cells, potentially in relation to the biosynthesis of nucleotide and supply of NADPH in one-carbon metabolism." (PMID 32368304, 2020). "Plus, MTHFD1L was reported by Agarwal et al33 that involved in the progression of colorectal cancer." (PMID 32285560, 2020). "This suggests that BBR may also play a role by directly targeting MTHFD1 and MTHFD1L in colorectal cancer cells." (PMID 38049785, 2023). "Next, we will further study the mechanism of MTHFD1L promoting metastasis of colorectal cancer." (PMID 32368304, 2020). "Studies have shown that an increased level of MTHFD1L may support colorectal cancer growth." (PMID 30269276, 2018). "The genes in the reported colorectal cancer group include POLR1D, DGKB, SULT2B1 SMPD1 GOT2, MTHFD1L and ACADM." (PMID 32285560, 2020).
hepatocellular carcinoma (6 papers, 2020 to 2024). A malignant tumor that arises from hepatocytes. "The elevation of oxidative stress through MTHFD1L knockdown or the use of methotrexate, an antifolate drug, sensitizes cancer cells to sorafenib, a targeted therapy for hepatocellular carcinoma." (PMID 39484215, 2024). "The folate cycle enzyme MTHFD1L is known to confer metabolic advantages in hepatocellular carcinoma." (PMID 39684755, 2024). "Genes involved in the biosynthesis of asparagine (Asns) and serine (Phgdh) and in folate metabolism (Mthfd1l and Mthfd2) were also elevated in Nod2−/− DMBA + HFD mice and are associated with the development of hepatocellular carcinoma." (PMID 33239685, 2020).
liver cancer (5 papers, 2020 to 2024). An epithelial or non-epithelial malignant neoplasm that arises from the liver. "MTHFD1L has metabolic advantage in liver cancer and can be used as a potential tumor marker of liver cancer." (PMID 35681277, 2023). "An early study identifies MTHFD1L in the folate cycle as an important metabolic pathway in liver cancer cells with the potential for therapeutic." (PMID 33605411, 2021). "The result showed that MTHFD1L was up-regulated in liver cancer compared with control sample." (PMID 33605411, 2021). "Down-regulating the expression of MTHFD1L made the liver cancer cells sensitive to sorafenib." (PMID 32368304, 2020). "The folic acid metabolizing enzyme MTHFD1L can generate NADPH to defend against oxidative stress and promote tumor growth in liver cancer." (PMID 38336749, 2024). "The results showed that MTHFD1L was a potential prognostic biomarker for LIHC, and could help to elucidate that how the immune microenvironment promotes liver cancer development." (PMID 33605411, 2021).
breast carcinoma (4 papers, 2018 to 2025). "Enhanced expression of mitochondrial folate cycle enzymes such as SHMT2, MTHFD2, and MTHFD1L was also detected in cancer cell lines using metabolic profiling, and this was associated with higher mortality in breast cancer patients." (PMID 38698089, 2024). "The formyl-tetrahydrofolate synthase activity of MTHFD1L has been reported to play an important role in the proliferation of breast cancer cells." (PMID 41154660, 2025). "AMPK indirectly downregulates expression of the 1C metabolism enzymes, MTHFD1, MTHFD1L and MTHFD2 in breast cancer, raising the possibility that AMPK activators may sensitize cancers to anti-folate therapy." (PMID 38698089, 2024). "With the exception of UQCRH and LRP8, the expression levels of genes positively correlated with YBX1, such as CTPS1, FMNL2, CDC20, B3GNT5, MTHFD1L, and CDCA8, were significantly and positively correlated with the expression level of YBX1 in 13 breast cancer cell lines." (PMID 30647855, 2018).
depression (4 papers, 2016 to 2021). "These few studies, implicating the roles of synaptic plasticity candidate genes BDNF and CREB1, as well as serotonin receptor gene HTR2A and folate pathway gene MTHFD1L, have exclusively focused on depression as a relevant disorder, or on depressive symptoms." (PMID 34577549, 2021). "In addition, rumination completely mediated the effects of MTHFD1L rs11754661 on depression phenotypes." (PMID 26926881, 2016). "We found MTHFD1L rs11754661 more consistently associated with ruminative response style than with our two depression phenotypes, as rs11754661 does not predict depression in the Manchester sample." (PMID 26926881, 2016). "Moreover, this association is only partly mediated by current depression score and lifetime depression, but ruminative response style fully explains the variance that MTHFD1L rs11754661 shares with these depression phenotypes." (PMID 26926881, 2016). "There is no obvious evidence for another core hub gene, MTHFD1L, to be associated with BD, but it is thought to have an important effect on the pathophysiology of depression through rumination, and maybe via this cognitive intermediate phenotype on other mental and physical disorders." (PMID 29257106, 2017).
bladder cancer (3 papers, 2022 to 2023). "A recent report revealed that MTHFD1L plays a vital role in bladder cancer by increasing cell proliferation, invasion and metastasis, however, their results were not validated further." (PMID 34908119, 2022). "Importance of folate metabolism in bladder cancer was further suggested by a study which demonstrated overexpression of folate enzyme MTHFD1L in muscle invasive bladder cancer tissues." (PMID 36500483, 2022). "Despite the significance of MTHFD1L in bladder cancer, CRC, ESCA and squamous cell carcinoma, knowledge regarding its role in other subtypes of human cancer is still unknown." (PMID 34908119, 2022).
esophageal cancer (3 papers, 2023 to 2025). A primary or metastatic malignant neoplasm involving the esophagus. "Serine hydroxymethyl transferase 2 (SHMT2) is involved in esophageal cancer progression by interacting with Methylenetetrahy-drofolate Dehydrogenase 1 Like (MTHFD1L), while hypoxia-induced SHMT2 Kla in turn enhanced MTHFD1L expression and accelerated the malignant progression of EC cells." (PMID 40563450, 2025). "In esophageal cancer, hypoxia stabilizes serine hydroxymethyltransferase 2 (SHMT2) via lactylation, which enhances its interaction with the key enzyme in one-carbon metabolism, methylenetetrahydrofolate dehydrogenase (NADP+ dependent) 1-like (MTHFD1L), thereby facilitating a malignant phenotype 57." (PMID 40128358, 2025).
osteosarcoma (3 papers, 2021 to 2024). A usually aggressive malignant bone-forming mesenchymal neoplasm, predominantly affecting adolescents and young adults. "Arbutin inhibits osteosarcoma cell proliferation, migration, and invasion via miR-338-3pl MTHFD1L (methylenetetrahydrofolate dehydrogenase (NADP+ Dependent) 1 Like) and by inactivating the AKT (protein kinase B)/mTOR (mammalian target of rapamycin) signaling pathway." (PMID 38958363, 2024). "It was suggested that arbutin could inhibit osteosarcoma cell proliferation, migration and invasion via miR-338-3pl MTHFD1L (methylenetetrahydrofolate dehydrogenase (NADP+ Dependent) 1 Like) and by inactivating the AKT (protein kinase B)/mTOR (mammalian target of rapamycin) signaling pathway." (PMID 36557918, 2022).
pancreatic cancer (3 papers, 2022 to 2023). "In summary, we found a potential circRNA, circ-MTHFD1L, associated with gemcitabine resistance in pancreatic cancer." (PMID 35459186, 2022). "To further study the prognostic significance of circ-MTHFD1L expression in pancreatic cancer patients, we tested the expression of circ-MTHFD1L in 96 pairs of pancreatic cancer tissues and normal tissues from gemcitabine-treated PADC patients." (PMID 35459186, 2022). "Circ-MTHFD1L can be stably expressed in various pancreatic cancer cell lines and localized in the cytoplasm." (PMID 35459186, 2022). "Through in-depth exploration, we discovered for the first time the key role of the circ-MTHFD1L/miR-615-3p/RPN6 axis in the process of chemotherapy resistance in pancreatic cancer." (PMID 35459186, 2022). "Silencing circ-MTHFD1L caused a decrease in BRCA1/2 expression or other unknown changes in BRCAness-associated proteins, undoubtedly pointing out a new direction for circ-MTHFD1L as a therapeutic target for pancreatic cancer." (PMID 35459186, 2022). "It is suggested that circ-MTHFD1L may be a new potential molecular marker for chemotherapy resistance of pancreatic cancer gemcitabine and a potential therapeutic target for combined treatment with olaparib." (PMID 35459186, 2022). "A metabolic crisis in pancreatic carcinoma cells was described after DMF treatment through the down-regulation of methylenetetrahydrofolate dehydrogenase (MTHFD1) and methylenetetrahydrofolate dehydrogenase (NADP+ Dependent) 1 Like (MTHFD1L), two enzymes implicated in folate metabolism." (PMID 36552824, 2022).
tongue squamous cell carcinoma (3 papers, 2019 to 2022). A squamous cell carcinoma that arises from the tongue. "Furthermore, MTHFD1L was also found to be associated with esophageal squamous cell carcinoma (ESCA) and tongue squamous cell carcinoma." (PMID 34908119, 2022). "The higher expression of MTHFD1L has been noted in multiple cancers including CRC, ESCA, and tongue squamous cell carcinoma." (PMID 34908119, 2022).
acute coronary syndrome (2 papers, 2014 to 2021). Signs and symptoms related to acute ischemia of the myocardium secondary to coronary artery disease. "The methylenetetrahydrofolate dehydrogenase 1-like (MTHFD1L) Rs6922269 SNP predicts mortality after acute coronary syndrome, and is a known risk loci for CAD." (PMID 34479557, 2021).
Alzheimer disease (1 paper, 2023). A progressive, neurodegenerative disease characterized by loss of function and death of nerve cells in several areas of the brain leading to loss of cognitive function such as memory and language. "Regional lookup places it downstream of MTHFD1L, which had been associated with late-onset Alzheimer’s disease and coronary artery disease." (PMID 36973338, 2023).
colorectal tumor (1 paper, 2020). "The relative quantitative analysis results showed that the expression of MTHFD1L in colorectal tumor tissue were significantly higher than those in the adjacent normal colorectal tissue (P<0.01)." (PMID 32368304, 2020).
dementia (1 paper, 2010). Loss of intellectual abilities interfering with an individual's social and occupational functions. "Although associations with experiment-wide statistical significance have not been observed for MTHFD1L in previous GWAS of LOAD, biological evidence suggests a role for this gene in dementia and AD pathology." (PMID 20885792, 2010).
head and neck cancer (1 paper, 2019). A primary or metastatic malignant neoplasm affecting the head and neck. "MTHFD1L was also found to be expressed at higher levels in head and neck cancer tissues than in normal tissues (P < 0.05) in several other studies." (PMID 31867267, 2019).
hepatoblastoma (1 paper, 2024). Hepatoblastoma (HB) is a malignant hepatic tumor and is the most common pediatric liver cancer. "One-carbon metabolism deregulation in hepatoblastoma tumors implicated 5-methyltetrahydrofolate-homocysteine methyltransferase (MTR), aldehyde dehydrogenase 1 family member L2 (ALDH1L2), and methylenetetrahydrofolate dehydrogenase (NADP+-dependent) 1-like (MTHFD1L)." (PMID 39684755, 2024).
lung carcinoma (1 paper, 2024). "Only PRDM16 and MTHFD1L are significantly enriched targets in miR-C2; miR-133, which is present in miR-C2, is reported to directly target and downregulate PRDM16 to regulate fat cell differentiation, and PRDM16 overexpression has been reported to inhibit EMT in lung cancer models." (PMID 38097740, 2024).
microphthalmia (1 paper, 2021). Congenital or developmental anomaly in which the eyeballs are abnormally small. "The results showed that knocking-down mthfd1L worsened eye malformation; whereas increasing mthfd1L expression at early stages before FD induction prevented microphthalmia in the mild-FD group." (PMID 34268314, 2021).
Mitochondrial myopathy (1 paper, 2017). "It was recently shown that mitochondrial myopathy mouse models with mtDNA replication disorders have increased protein levels of the mitochondrial 1C pathway enzymes MTHFD2 and MTHFD1L, as well as increased transcript levels of the genes encoding for key enzymes of the serine synthesis pathway." (PMID 29132502, 2017).
neural tube defect (1 paper, 2012). A congenital defect characterized by failure of the neural tube to close completely; this results in the presence of openings in the brain or spinal cord. "Polymorphisms within the MTHFD1L gene were previously associated with risk of neural tube defects in Ireland." (PMID 22520921, 2012). "Based on its association with neural tube defects (NTDs), and the previously detected association of its cytoplasmic homologue MTHFD1 in our cleft cohort, we considered the mitochondrial enzyme MTHFD1L to be a prime candidate for consideration for association with cleft." (PMID 22520921, 2012).
non-small cell lung carcinoma (1 paper, 2019). A group of at least three distinct histological types of lung cancer, including non-small cell squamous cell carcinoma, adenocarcinoma, and large cell carcinoma. "MTHFD1L silencing reduced proliferation and enhanced the apoptosis of non-small cell lung cancer by suppressing DNA methylation." (PMID 31867267, 2019).
Obesity (1 paper, 2020). Accumulation of substantial excess body fat. "Only six out of the 81 mitochondrial protein-encoding genes showed higher expression in the obesity-risk genotype (SEPT4, PYCR1, PRELID2, CPT1A, MTHFD1L, and FKBP10)." (PMID 32316277, 2020).
oral cancer (1 paper, 2023). "The synthesized MTHFD1L shRNA nanoparticles can be used to treat oral cancer." (PMID 35681277, 2023).